TMEM43 (transmembrane protein 43)
Description:
May have an important role in maintaining nuclear envelope structure by organizing protein complexes at the inner nuclear membrane. Required for retaining emerin at the inner nuclear membrane (By similarity). Plays a role in the modulation of innate immune signaling through the cGAS-STING pathway by interacting with RNF26. In addition, functions as a critical signaling component in mediating NF-kappa-B activation by acting downstream of EGFR and upstream of CARD10. Contributes to passive conductance current in cochlear glia-like supporting cells, mediated by gap junctions and necessary for hearing and speech discrimination.
Synonyms: MGC3222; DKFZp586G1919; LUMA; ARVC5; ARVD5; AUNA3; EDMD7; EDMD7; AUNA2
Tractability: Antibody: UniProt places it where antibodies can reach, with high confidence; UniProt predicts a signal peptide or a membrane-spanning region; its Gene Ontology location is reachable by antibodies, with medium confidence. PROTAC: ubiquitination databases record sites on it; its protein half-life has been measured.
Gene: Protein-coding gene on chromosome 3 (14,125,015 to 14,143,681, forward strand). Ensembl gene ENSG00000170876.
Subcellular location: Endoplasmic reticulum membrane; Nucleus inner membrane; Cell membrane
Gene Ontology:
Molecular function: identical protein binding; protein binding; voltage-gated monoatomic cation channel activity; voltage-gated potassium channel activity; voltage-gated sodium channel activity
Biological process: metal ion transport; nuclear membrane organization; potassium ion transport; sodium ion transport; lipid metabolic process; monoatomic cation transmembrane transport; potassium ion transmembrane transport; sodium ion transmembrane transport
Cellular component: endoplasmic reticulum membrane; Golgi apparatus; plasma membrane; nuclear inner membrane; endoplasmic reticulum lumen
Genetic constraint (gnomAD): Loss-of-function variants: 45 observed, 51.04 expected, observed/expected ratio (o/e) 0.88, 90% interval 0.69 to 1.13. The upper end of that interval is the gene's LOEUF score, 1.13, which puts it in group 4 of 6, group 1 being the genes least tolerant of losing a copy. Missense variants: 532 observed, 540.88 expected, observed/expected ratio (o/e) 0.98, 90% interval 0.92 to 1.06. Synonymous variants: 199 observed, 218.87 expected, observed/expected ratio (o/e) 0.91, 90% interval 0.81 to 1.02.
Gene-disease validity (ClinGen):
ClinGen rates the evidence that TMEM43 causes each of these diseases.
arrhythmogenic right ventricular dysplasia 5 (autosomal dominant): Definitive. Any arrhythmogenic right ventricular cardiomyopathy in which the cause of the disease is a mutation in the TMEM43 gene.
Homologues: Orthologues: chimpanzee TMEM43 (99% identical), macaque TMEM43 (97% identical), mouse Tmem43 (93% identical), dog TMEM43 (92% identical), guinea pig TMEM43 (92% identical), rabbit TMEM43 (92% identical), pig TMEM43 (91% identical), rat Tmem43 (84% identical), tropical clawed frog tmem43 (61% identical), Drosophila melanogaster Tmem43 (30% identical).
Diseases named in the same sentence as TMEM43 in open-access papers:
TMEM43 is named in the same sentence as 77 diseases in open-access papers, as found by Europe PMC text mining. Sharing a sentence is not in itself a finding about the gene and the disease. The quoted sentences say what the papers report.
arrhythmogenic right ventricular cardiomyopathy (20 papers, 2012 to 2026). "Arrhythmogenic right ventricular cardiomyopathy type 5 is caused by the missense mutation S358L in the gene TMEM43 in humans." (PMID 41873591, 2026). "For example, the deficiency of TMEM43 is widely thought to cause arrhythmogenic right ventricular cardiomyopathy type 5 (ARVD5)." (PMID 37064154, 2023). "As a four-transmembrane protein anchored to the endoplasmic reticulum, a previous study found TMEM43 mutation causes arrhythmogenic right ventricular dysplasia/cardiomyopathy and TMEM43 was also reported to be associated with pro-fibrotic cardiomyopathy." (PMID 36230956, 2022). "A previous study found that transmembrane protein 43 (TMEM43) was highly associated with arrhythmogenic right ventricular dysplasia/cardiomyopathy." (PMID 36230956, 2022). "The Ser358Leu mutation in TMEM43, encoding an inner nuclear membrane protein, has been implicated in arrhythmogenic right ventricular cardiomyopathy (ARVC)." (PMID 22458570, 2012). "A missense mutation, S358L, in TMEM43 is linked to the development of arrhythmogenic right ventricular cardiomyopathy type 5 (ARVC5), a highly penetrant and lethal type with right ventricular dilation, fibro-fatty replacement of cardiomyocytes, heart failure, and early death." (PMID 40885397, 2025). "Moreover, it has been shown that the gene TMEM43 is associated with a unique form of arrhythmogenic right ventricular cardiomyopathy (ARVC)." (PMID 34066119, 2021). "Previously, p.(Ser358Leu) in TMEM43 has been shown to cause familial arrhythmogenic right ventricular cardiomyopathy (ARVC)." (PMID 34050020, 2021). "Other nuclear envelope proteins, such as TMEM43 (p.S358L), have been related to arrhythmogenic right ventricular cardiomyopathy, generating a high rate of MVA." (PMID 38337354, 2024). "The most frequent in the ACMG SFs were gene/disease and frequency TTN DCM (four times); KCNQ1 LQTS (three times); MYBPC3 HCM (two times); TMEM43 arrhythmogenic right ventricular cardiomyopathy (two times); PALB2 HBC (two times); and RYR1 MH (two times)." (PMID 36635046, 2023). "The transmembrane protein 43 (TMEM43) S358L mutation is the most common mutation found in patients with ARVC5, a severe subtype of arrhythmogenic right ventricular cardiomyopathy (ARVC)." (PMID 41411330, 2025).
cardiomyopathy (20 papers, 2012 to 2025). A disease of the heart muscle or myocardium proper. "In previous studies, immunoprecipitation experiments were performed to understand the molecular mechanisms underlying TMEM43p.S358L-related cardiomyopathy and to identify possible interaction partners of the wild-type and mutant TMEM43 proteins." (PMID 41236655, 2025). "A haploinsufficiency of Tmem43 in murine cardiac myocytes has been shown to cause senescence-associated cardiomyopathy via the DNA damage response (DDR) pathway." (PMID 40725103, 2025). "The main outcomes associated with TMEM43 cardiomyopathy are arrhythmic events, which typically occur at an early stage, and HF." (PMID 40869437, 2025). "In conclusion, our findings suggest ultrastructural remodeling and transcriptomic alterations underlying the development of structural and functional cardiac defects in TMEM43-associated cardiomyopathy." (PMID 36076925, 2022). "A previous study found that TMEM43 mutation causes arrhythmogenic right ventricular dysplasia/cardiomyopathy." (PMID 36230956, 2022). "Taken together, these results suggesteda direct causal effect of TMEM43-S358L mutation resulting inbiventricular cardiomyopathy phenotype." (PMID 34766515, 2022). "Other TMEM43-related cardiac pathologies include reduced expression of Tmem43 during cardiac hypertrophy that leads to worsening heart failure in mice, while haplo-deficiency of Tmem43 that results in age-dependent late-onset senescence-associated cardiomyopathy via the DDR pathways." (PMID 40725103, 2025). "Moreover, it was also found that overexpression of wild-type and p.P111L-mutant TMEM43 in a transgenic zebrafish model was associated with cardiac enlargement and cardiomyocyte hypertrophy, which confirms the role of transcriptomic alterations in the pathogenesis of TMEM43-associated cardiomyopathy." (PMID 40722594, 2025). "Next, since common mechanisms often underlie each cardiomyopathy even in the setting of genetic heterogeneity, we conducted in vitro studies to determine whether the functional abnormalities caused by the rare TMEM43 S358L parallel those found in the setting of desmosomal mutations." (PMID 22458570, 2012). "Through a systematic approach, this review sought to assess the natural history and electrocardiographic and imaging findings as well as the clinical outcomes of TMEM43 cardiomyopathy." (PMID 40869437, 2025). "This review aimed to systematically synthesize the current evidence on the natural history, electrocardiographic, and imaging findings as well as the clinical outcomes of TMEM43 cardiomyopathy." (PMID 40869437, 2025). "Patients with TMEM43 cardiomyopathy exhibited distinct electrocardiographic characteristics, including PRWP, QRS prolongation, and the presence of PVCs on baseline ECGs." (PMID 40869437, 2025). "HF is typically a late clinical manifestation of TMEM43 cardiomyopathy, requiring HT in a minority of cases." (PMID 40869437, 2025). "TMEM43 cardiomyopathy is a rare form of ACM characterized by a fully penetrant autosomal dominant inheritance and sex-related differences in phenotypic expression, including severe arrhythmic events and LV dysfunction." (PMID 40869437, 2025). "Overexpression of TMEM43 inhibited LPS-induced ferroptosis with increased levels of SLC7A11 and GPX4, revealing a protective role of TMEM43 against sepsis-induced cardiomyopathy." (PMID 39318361, 2024). "In human patients, mutations in the nuclear envelope protein TMEM43 are linked to severe diseases, including ACM type 5, a devastating cardiomyopathy that leads to malignant arrhythmias and heart failure." (PMID 38999368, 2024). "Recent findings reveal a role of islet cell autoantigen 69 (ICA69)-STING signaling and transmembrane protein 43 (TMEM43) in lipopolysaccharide (LPS)-induced cardiomyocyte ferroptosis and cardiomyopathy." (PMID 39318361, 2024).
cardiomyopathy (continued). "The transmembrane protein 43 (TMEM43), a transmembrane protein related to cardiomyopathy, protects against SCM by inhibiting ferroptosis in LPS-induced mice." (PMID 37138856, 2023). "The knockdown of TMEM43 in the heart aggravates LPS-induced cardiomyopathy, accompanied by an increased cardiac ferroptosis." (PMID 37138856, 2023). "In human patients, mutations in the nuclear envelope protein TMEM43 are responsible for severe diseases, including ACM type 5, a devastating cardiomyopathy that causes malignant arrhythmias and heart failure." (PMID 36076925, 2022). "Mutations in TMEM43 are associated with varied diseases in humansincluding ARVC5, a severe form of cardiomyopathy with malignant arrhythmias andsudden cardiac death." (PMID 34766515, 2022). "TMEM43 cardiomyopathy is characterized by a well-defined clinical and instrumental phenotype." (PMID 40869437, 2025). "Furthermore, mutant TMEM43 did not alter the expression of genes as observed in the cardiomyopathy caused by mutations in the nuclear membrane-associated protein, lamin A/C." (PMID 22458570, 2012). "In TMEM43 cardiomyopathy, patients may exhibit a non-ischemic pattern of LGE, most commonly in the subepicardial region; however, myocardial fibrosis may be absent in some cases." (PMID 40869437, 2025). "Advances in genetic characterization of cardiomyopathies have identified some desmosomal genes such as DSP and non-desmosomal genes such as Phospholamban, Filamin-C, and Transmembrane Protein 43, that are often associated with biventricular or LV-dominant subforms." (PMID 40021092, 2025). "In contrast, for rare cardiomyopathy genes, e.g., TMEM43, no iPSC lines have been developed yet." (PMID 31489928, 2019).
Arrhythmia (8 papers, 2022 to 2026). Any cardiac rhythm other than the normal sinus rhythm. "Decreasing interaction of VDAC2 and TMEM43 in mutant cells may change the cellular localization of VDAC2 and influence mitochondrial Ca2+ uptake, leading to effects like arrhythmia, fibrosis that are found in TMEM43 S358L associated ARVC." (PMID 41411330, 2025). "ACM patients with high serum levels of oxLDL, including those carrying the TMEM43 mutation, have worse clinical phenotypes presenting as higher fat displacement of myocytes, ventricular dysfunction, and risk of having a severe, potentially lethal cardiac arrhythmia." (PMID 40725103, 2025). "KCNQ1/KCNH2 suppression-and-replacement, SCN5A base editing, and structural protein restoration via PKP2 and TMEM43 have each demonstrated capacity to re-establish electrophysiological stability in arrhythmia models." (PMID 42193469, 2026). "Current recommendations advise that patients with left ventricular ejection fraction ≤ 40%, exercise-induced arrhythmias, or pathogenic variants in LMNA, TMEM43, or filamin C refrain from vigorous exercise or competitive sports, even if protected by an ICD." (PMID 41464586, 2025). "Adipogenic conditions are thought to play an important role in the formation of arrhythmia substrates in ARVC5 induced by TMEM43." (PMID 40725103, 2025). "In summary, the S358L TMEM43 mutation causes severe cardiac arrhythmias, SCD, and progressive HF in animal models characteristic of human ARVC5 by disrupting the structural integrity, cell-to-cell adhesion, and gap junction function of cardiomyocytes." (PMID 40725103, 2025). "This comprehensive approach allowed us successfully uncover the pathological characteristics associated with TMEM43‐related ARVC and to elucidate the molecular mechanisms underlying the increased propensity for cardiac arrhythmias observed in TMEM43‐related ARVC." (PMID 40948388, 2025). "Some studies reported the Newfoundland TMEM43 S358L gene variant in males being associated with very high permeability and arrhythmia risk rather than in females." (PMID 39845823, 2024). "Crucially, the underlying mechanisms of arrhythmia associated with TMEM43 and, especially, the early concealed phase are not well understood." (PMID 36294819, 2022). "Patient‐specific iPSC‐CMs carrying TMEM43‐P386S exhibited a series of baseline electrophysiological abnormalities at the single‐cell and multicellular levels, including DAD and PCF arrhythmias, beating interval variation, slower depolarization, and conduction defect." (PMID 40948388, 2025). "Importantly, however, we did not observe any arrhythmia substrates in TMEM43 S358L monolayers in the absence of adipogenic conditions over a similar duration, suggesting the mutation alone in myocytes is not sufficient to explain early arrhythmogenesis." (PMID 36294819, 2022).
Emery-Dreifuss muscular dystrophy (6 papers, 2012 to 2021). Emery-Dreifuss muscular dystrophy (EDMD) is characterized by muscular weakness and atrophy, with early joint contractures and cardiomyopathy. "Since mutations in emerin cause Emery-Dreifuss muscular dystrophy and TMEM43 can affect emerin distribution, it has been suggested that TMEM43 mutations could result in muscular dystrophy." (PMID 22458570, 2012). "Emery-Dreifuss muscular dystrophy (EDMD) was initially linked to mutations in the EMD gene, which encodes the INM protein emerin, but can also be caused by mutations in LMNA and NE genes SYNE1, SYNE2 and TMEM43." (PMID 24490688, 2014).
brain tumor (4 papers, 2018 to 2023). "What’s more, TMEM43 upregulation has been closely associated with malignant brain tumors, and the inhibition of TMEM43 expression inhibited the growth of brain tumor cells in vitro and in vivo." (PMID 37064154, 2023). "Previous studies indicated that TMEM43 facilitated brain tumor progression by mediating EGFR-induced NF-κB activation and promoting the phosphorylation of ERK." (PMID 35260078, 2022). "The upregulation of TMEM43 in brain tumor cells accelerated brain tumor progression through the interaction of TMEM43 with CARD-containing MAGUK protein 3 (CARMA3) in the EGFR-induced NF-κB pathway." (PMID 35260078, 2022). "Reports on brain tumors highlighted upregulation of TMEM-43 as a major contributor to poor survival and patient outcomes." (PMID 34571860, 2021). "verified that high TMEM43 expression was closely related to brain tumor malignancy, and inhibiting the expression of TMEM43 in brain tumor cells could lead to its growth in vitro and in vivo." (PMID 37064154, 2023). "Interestingly, they found that TMEM43 is highly expressed in glioblastoma multiforme and that high TMEM43 expression correlates with poor survival outcome in patients with brain tumors." (PMID 30158935, 2018).
pancreatic cancer (4 papers, 2022 to 2025). "Kaplan–Meier curve analysis was performed to assess the association between the TMEM43 level and survival of pancreatic cancer patients." (PMID 35260078, 2022). "Taken together, these results suggest that TMEM43 could be used as a diagnostic biomarker and therapeutic target for patients with pancreatic cancer." (PMID 35260078, 2022). "Knock-down of TMEM43 in vitro inhibited pancreatic cancer progression, dysregulated the cell cycle, and promoted tumorigenicity in vivo." (PMID 40725103, 2025). "Collectively, these results suggest that TMEM43 mediates pancreatic cancer progression through the PRPF3/RAP2B/ERK signaling pathway." (PMID 35260078, 2022). "TMEM43 was also identified as an independent predictive biomarker for the prognosis in patients with pancreatic cancer by multivariate analysis (p = 0.016)." (PMID 35260078, 2022). "The result of TMA cohort 1 samples from pancreatic cancer patients further confirmed that TMEM43 expression level was obviously elevated in pancreatic cancer samples compared with control samples using IHC (p < 0.0001)." (PMID 35260078, 2022). "We further demonstrated that TMEM43 promoted pancreatic cancer progression via the RAP2B/ERK pathway." (PMID 35260078, 2022). "Knockdown of TMEM43 inhibited pancreatic cancer progression in vitro, decreased the percentage of S phase, and inhibited the tumorigenicity of pancreatic cancer in vivo." (PMID 35260078, 2022). "To assess the function of TMEM43 in pancreatic cancer, we first established stable TMEM43 knockdown in MIAPaCa-2 cells and TMEM43-overexpression in TMEM43-silenced MIAPaCa-2 cells." (PMID 35260078, 2022). "Coimmunoprecipitation (co-IP) followed by protein mass spectrometry was applied to analyze the molecular mechanisms of TMEM43 in pancreatic cancer." (PMID 35260078, 2022). "TMEM43 expression was also upregulated in five paired pancreatic cancer tissue samples and peritumoral samples using western blotting, and one sample pair was used to further confirm the result by IHC staining." (PMID 35260078, 2022). "We demonstrated that TMEM43 expression level is elevated in pancreatic cancer samples compared with control group, and is correlated with poor DFS and OS in pancreatic cancer patients." (PMID 35260078, 2022). "In summary, our findings identify TMEM43 as a putative novel oncogene, the expression of which is upregulated in pancreatic cancer." (PMID 35260078, 2022). "Our study provides novel insights into the underlying molecular mechanisms of pancreatic cancer and highlights TMEM43 as a novel potential prognostic marker and therapeutic target for pancreatic cancer." (PMID 35260078, 2022). "Taken together, these results suggest that TMEM43 promotes pancreatic cancer progression through the RAP2B/ERK axis." (PMID 35260078, 2022). "In our study, we showed that TMEM43 expression levels were higher in pancreatic cancer samples than in control samples, and pancreatic cancer patients with higher TMEM43 expression levels had shorter OS and DFS." (PMID 35260078, 2022). "Collectively, these results suggest that TMEM43 facilitates the growth, migration, and invasion of pancreatic cancer in vitro." (PMID 35260078, 2022). "Receiver operating characteristic (ROC) curve analysis suggested that TMEM43, PRPF3, and RAP2B had good diagnostic value in pancreatic cancer patients according to their prognostic value in the GSE62452, GSE16515, GSE28735, and GSE15471 datasets." (PMID 35260078, 2022). "In this study, TMEM43 expression levels were analyzed in pancreatic cancer samples compared with control samples." (PMID 35260078, 2022). "We further assessed the effect of TMEM43 via regulating PRPF3/RAP2B axis on pancreatic cancer cell growth in vivo." (PMID 35260078, 2022). "In vitro and in vivo assays were performed to explore the function and role of TMEM43 in pancreatic cancer." (PMID 35260078, 2022).